POLR2A (RNA polymerase II subunit A)
Diseases named in the same sentence as POLR2A in open-access papers (continued):
Sharing a sentence is not in itself a finding about the gene and the disease.
cancer (continued). "Using a 7,781-sample pan-cancer dataset, we first confirmed this in POLR2A, an essential gene where hemizygous deletions are known to confer elevated sensitivity to pharmacological suppression." (PMID 28027311, 2016). "This interaction with nuclear CD26 and POLR2A gene consequently led to transcriptional repression of the POLR2A gene, resulting in retarded cell proliferation of cancer cells." (PMID 23638030, 2013). "It was previously reported that blockade of POLR2A function by RNAi strategies, and treatment with chemical compounds such as α-amanitin, resulted in growth inhibition of cancer cells." (PMID 23638030, 2013). "In conclusion, the present data provides evidence that induced nuclear localization of CD26 by the humanized anti-CD26 mAb, YS110, promotes transcriptional repression of the POLR2A gene, resulting in growth suppression of cancer cells." (PMID 23638030, 2013). "Notably, early studies of the GEMINI genes POLR2A and RPA1 achieved allele-specific growth suppression of cancer cells using ASO4,61,62 and RNAi63 reagents." (PMID 32433464, 2020). "Inhibiting POLR2A will be a novel therapeutic approach for human cancers." (PMID 31775867, 2019). "Taken together, these results suggest that POLR2A may provide a meaningful therapeutic target for cancers." (PMID 23638030, 2013). "To investigate whether the nuclear translocation of CD26 suppresses POLR2A expression, we first evaluated POLR2A expression in cancer cells after YS110 treatment, as YS110 induced the nuclear localization of CD26." (PMID 23638030, 2013). "Trio‐based clinical exome sequencing, performed on genomic DNA obtained from leukocytes (Twist Bioscience, South San Francisco, CA), did not reveal any cancer‐associated pathogenic variant, but revealed a novel de novo POLR2A missense variant, c.3865G > A (p.Glu1289Lys)." (PMID 35689525, 2022). "Therefore, they concluded that POLR2A inhibition is lethal in human cells and could be considered a novel treatment approach for human cancers." (PMID 35012286, 2021). "At present, it remains to be investigated whether nuclear expression of JAK3 involves interaction with POLR2A in healthy, non-malignant T cells or whether this interaction is a unique, cancer-associated feature of malignant T cells." (PMID 33466582, 2021). "Similarly, it was recently shown that HeZD of the essential gene POLR2A, a subunit of RNA polymerase II, creates a therapeutic vulnerability, as cancer cells carrying only a single functional copy of the gene are more sensitive to inhibition of its protein product." (PMID 28027311, 2016). "A majority of the previously unpublished genes have been associated with tumorigeneses and tumor-suppressor pathways, primarily in cancer phenotypes, including: SLC16A11, POLR2A, C11orf87, and SLC12A747–52." (PMID 40050615, 2025). "Intriguingly, cancer cells display analogous dependencies, exploiting POLR2A/RPB1 dysregulation to sustain aberrant transcriptional programs and survive genotoxic stress." (PMID 41487511, 2025).
cancer (continued). "Extensive in vitro and in vivo analyses demonstrated that PTf‐SRiApt preferentially suppresses the proliferation of “transcriptionally addicted” TNBC cancer cells with heightened SCAF4 and POLR2A expression." (PMID 40574704, 2025). "Recent results have underscored the pivotal role of POLR2A/RPB1 dysregulation in driving tumor growth and progression across various cancer types." (PMID 41487511, 2025). "Intriguingly, similar principles appear to operate in cancer, where POLR2A/RPB1 dysregulation fuels transcriptional addiction and malignant progression." (PMID 41487511, 2025). "To answer the question whether POLR2A participates in the USP10‐medidated transcriptional activation of SLC7A11 and inhibition of cancer ferroptosis, we knocked down the expression of POLR2A in USP10‐overexpressed Cal27 cells." (PMID 40605431, 2025). "The notably high overlapping ratios were discerned for TFs playing critical roles in transcription pre-initiation or RNA polymerase activities, e.g., UBTF, TAF1, and POLR2A, in addition to others, like E2F6, IRF1, and MYC, which are involved in cancer-related processes." (PMID 36092921, 2022). "Induction of nuclear localization of CD26 by Y-TR1 promotes transcriptional repression of the POLR2A gene, furthermore the internalization of YS110-TR1 compound into the nucleus may inhibit TFIIH, resulting in impaired cancer cell growth." (PMID 31398954, 2019). "In this study, we examined the significance of the nuclear localization of CD26 in its role as a mAb therapy for CD26-positive cancers, and showed that nuclear translocation of CD26 induced by YS110 treatment reduces cell growth through transcriptional repression of the POLR2A gene." (PMID 23638030, 2013). "Because POLR2A is a protein-coding gene, identifying potential open reading frames within circPOLR2A isoforms may also shed light on noncanonical translation events in cancer." (PMID 41487511, 2025).
tumor (45 papers, 2011 to 2025). "Silencing of POLR2A using a pH-sensitive nanobomb incorporated with a POLR2AsiRNA (siPol2) and guanidine–CO2 functionalized chitosan at neutral pH led to an effective growth inhibition of TNBC tumor characterized by hemizygous loss of POLR2A." (PMID 39199788, 2024). "After surgical removal of the tumor, he had a progressively ingravescent neurological condition, and genetic studies documented a previously unreported de novo germline POLR2A variant." (PMID 35689525, 2022). "However, POLR2A mutation was a risk factor for the tumor recurrence (p = 1.7 × 10−2, Hazard Ratio 4.08, 95% Confidence Interval 1.28–13.0)." (PMID 33772057, 2021). "Patients harboring POLR2A mutations experienced tumor recurrence with a high rate of 29.4%." (PMID 33772057, 2021). "We found that the POLR2A‐lncRNA signature could significantly subdivide patients into different risk subgroups within different levels of age, grade, stage and residual tumour diameter." (PMID 30549251, 2019). "To determine whether purifying selection acts on POLR2A, we pooled together somatic mutation and copy number data from 7,871 tumor samples, spanning 25 different tumor types, from The Cancer Genome Atlas (TCGA)." (PMID 28027311, 2016). "Interestingly, the polyadenylation factor CstF associated to the tumor suppressors BRCA1/BARD1 play a role in the proteasome-mediated degradation of POLR2A during DDR." (PMID 27462460, 2016). "Moreover, a recent retrospective study reported, especially for WHO grade I skull‐base meningiomas, POLR2A pathogenic variants found in tumor samples could be a potentially ideal marker of significantly worse prognosis and a suitable predictor of recurrence." (PMID 35689525, 2022). "In summary, these results further confirm that PF-3758309 inhibits tumor cell growth by promoting the ubiquitination-dependent degradation of POLR2A/B/E." (PMID 40854914, 2025). "These nanoparticles accumulated in both POLR2Aneutral and POLR2Aloss tumors, but inhibition of POLR2A significantly reduced tumor growth in heterozygous POLR2Aloss tumors, still avoiding systemic side effects." (PMID 41487511, 2025). "DDB2 has been implicated in the regulation of DNA damage repair and protein degradation, and our results indicate that DDB2-mediated ubiquitination of POLR2A/B/E is a key driver of PF-3758309’s anti-tumor effects." (PMID 40854914, 2025). "Functional assays confirmed that PF-3758309 inhibits tumor cell growth and migration by promoting ubiquitination-dependent degradation of POLR2A/B/E." (PMID 40854914, 2025). "While our research supports the efficacy of PF-3758309 in promoting tumor cell death through POLR2A/B/E degradation, several challenges remain." (PMID 40854914, 2025). "By promoting the ubiquitination and subsequent degradation of POLR2A/B/E, PF-3758309 disrupts transcription and induces apoptosis in tumor cells." (PMID 40854914, 2025). "Collectively, our proteomics, transcriptomics, and ubiquitinomics data suggest that PF-3758309 inhibits tumor growth by regulating the ubiquitination-dependent degradation of POLR2A/B/E." (PMID 40854914, 2025). "Del17p has been associated with reduced copy number and gene expression of RNA polymerase II subunit alpha (POLR2A) in other tumor types." (PMID 38260385, 2024). "Our previous results assessing reference genes in Sq-NSCLC showed that GAPDH gene expression was diverse and unstable in tumor and tumor-adjacent normal tissue samples, whereas POLR2A and ACTB expression levels were the most stable among analyzed samples." (PMID 36142417, 2022).
tumor (continued). "Highly expressed POLR2A was associated with the poor prognosis of TNBC patients, inhibition of POLR2A would reduce tumor growth." (PMID 34899822, 2021). "Thereafter, we comprehensively evaluated the associations between tumor location (embryological origin), pathological diagnosis (histological type), and driver mutations including AKT1, KLF4, SMO, POLR2A, and NF2 mutations." (PMID 33772057, 2021). "We examined the expression of POLR2A at mRNA and protein levels in 39 GC patients’ GC tissue samples and adjacent normal (non-tumor) tissue samples by qRT-PCR and IHC staining." (PMID 34899822, 2021). "Herein it revealed that in contrast to this ErbB2-Herceptin line, the YS110 treatment abundantly induces nuclear localization of CD26 and in consequentially suppresses POLR2A expression, leading to inhibition of tumor cell growth." (PMID 31398954, 2019). "Our omics data suggest that PF-3758309 may inhibit tumor growth by regulating the ubiquitination-dependent degradation of POLR2A/B/E." (PMID 40854914, 2025). "Last, the density map of the detected transcripts provides a visual method to identify spatial localization of clusters of genes, such as KI67 (indicative of proliferating tumor cells) being more prevalent in the dermis region while POLR2A is dispersed throughout the region." (PMID 35013281, 2022). "The selected candidate biomarkers were then validated on HNSCC patient tissue specimens by RT-qPCR which provided quantitative data on expression of these selected genes (relative to two reference genes YAP1 and POLR2A) on paired margin and tumour core tissue samples." (PMID 31443700, 2019). "This is likely because of varying degrees of mRNA degradation that may occur during processing and storage of FFPE material, together with potential inter-tumor heterogeneity in POLR2A mRNA expression." (PMID 29222441, 2017). "Moreover, studies suggest that POLR2A/RPB1 interacts with various proteins to form regulatory networks that may drive aggressive tumor behavior and affect treatment responses." (PMID 41487511, 2025). "POLR2A, as the core of the transcription mechanism, is considered to be an essential transcriptional oncogene and anti-apoptotic factor, which could maintain the rapid growth and apoptosis resistance of tumor cells." (PMID 34899822, 2021). "Therefore, POLR2A is highly expressed in tumor tissues compared with normal tissues." (PMID 34899822, 2021). "Therefore, we examined whether the novel Antibody-drug conjugate (ADC), Y-TR1 (YS110-TR1 conjugate), restrained POLR2A expression more strongly in the nucleus of tumor cells than YS110 alone." (PMID 31398954, 2019). "PTf‐SRiApt effectively inhibits tumor growth and induces cell cycle arrest in TNBC cells with elevated SCAF4 and POLR2A expression." (PMID 40574704, 2025). "In conclusion, our study reveals a novel anti-tumor mechanism of PF-3758309, which involves the DDB2-mediated degradation of POLR2A/B/E through the ubiquitin-proteasome system." (PMID 40854914, 2025). "Up-regulation of ten DEGs in PAAD tumor is in concordance with the up-regulation of master regulators CTCF, IRF1, and KLF4, while POLR2A and STAG1 remain unchanged." (PMID 35453789, 2022). "POLR2A was pulled down by BCAR1 in 293T cells, probably due to tissue‐specific or tumor‐specific interactions between these two proteins." (PMID 33001583, 2020). "Through suppressing the transcription of POLR2A, the type II glycoprotein CD26 plays an inhibitory role in tumor growth." (PMID 31885751, 2019). "We observed significant over-expression of ADAR, ADARB1, DDX5/17/20, DGCR8, DICER1, DROSHA, EIF2C1-4 (AGO1-4), GEMIN4, POLR2A, TARBP2, TNRC6A and XPO5 in tumor tissue compared to adjacent mucosa." (PMID 31510013, 2019). "Three positive control probes, POLR2A, PPIB and UBC were applied to FFPE sections from a range of tumour types in FFPE whole-face (prospective collection) or TMA (retrospective collection) formats and evaluated semi-quantitatively and by image analysis." (PMID 29212158, 2017).
tumor (continued). "Quantification of POLR2A, PPIB and UBC was performed using Spotstudio software in 6 distinct regions of interest (ROI), 3 from tumour and 3 from stromal compartment of each tissue block." (PMID 29212158, 2017). "Tumour tissue and normal tissue group of five candidate reference genes (CASC3, CDKN1B, POLR2A, PUM1 and UBC) were statistically equivalent to within ± 1.5." (PMID 21806841, 2011). "CircMETTL6 acts as a tumor suppressor by interfering with NONO's interaction with POLR2A, leading to decreased GDF15 transcription." (PMID 39899667, 2025). "YS110 has an inhibitory activity against the CD26-positive tumor growth via the immunological and direct pathway, such as intra-nuclear transportation of CD26 and YS110, and suppressed transcription of RNA polymerase II (Pol II) subunit POLR2A." (PMID 31398954, 2019). "In our sample set, we did not observe any atypical tumours that harboured mutations in TRAF7/KLF4, POLR2A or the Hedgehog pathway." (PMID 28195122, 2017). "The results of our analysis proved that the expression of reference genes in our cohort of patients, including only endometrioid histotype and carefully selected and balanced according to their tumor grade, was dependent on tumor grade for B2M, GAPDH, H3F3A, GUSB, HPRT1, POLR2A and UBC." (PMID 25473950, 2014). "Global transcriptomic profiling showed that POLR2A knockout markedly suppressed oncogenic and antiapoptotic genes, including MYC, RUNX2, MEIS1, CDC25A, and BCL-2, leading to impaired proliferation and a significant reduction in tumor cell populations at 7 and 14 days after implantation in vivo." (PMID 41487511, 2025). "Neither BCAR1 nor POLR2A expression was correlated with tumor size (data not shown)." (PMID 33001583, 2020). "To identify the functional effect of ANAPC1 rs3814026C>T, ETS2 rs461155A>G, SORBS1 rs7081076C>A and POLR2A rs2071504C>T, we evaluated the relationship between the genotypes of those SNPs and mRNA expression of each gene in tumor and paired non-malignant lung tissues." (PMID 26893365, 2016). "However, POLR2A expression level was not different between tumor and normal tissues." (PMID 26893365, 2016).
infection (17 papers, 2014 to 2026). The state of being infected such as from the introduction of a foreign agent such as serum, vaccine, antigenic substance or organism. "We observed that an RNA polymerase II subunit A (POLR2A) targeting sgRNA, which was used as a positive control, caused a rapid depletion of transduced cells within 4–7 days post infection." (PMID 32180900, 2020). "To determine whether transcriptional host shut off and tRNA upregulation may be linked phenomena, we performed ChIP-Seq for POLR2A on human fibroblasts after infection with ∆ICP0/4/22/27/47, ∆ICP4, ∆ICP27, ∆ICP22, and wildtype HSV-1 for 6 h." (PMID 35110532, 2022). "Of the mutants tested, ∆ICP0/4/22/27/47 infection had the lowest level of POLR2A recruitment to tRNA loci." (PMID 35110532, 2022). "WT MHV68 infection reduced the levels of Pol II subunits Polr2a (Rpb1), Polr2b (Rpb2) and Gtf2B (TFIIB) beginning at 20 hpi." (PMID 32032393, 2020). "Therefore, we measured mRNA levels of RNA polymerase II subunit A (POLR2A), encoding the largest subunit of the polymerase responsible for mRNA transcription in eukaryotic cells, in both HSV-1 and HSV-2 infected neurons at 6 days post-infection." (PMID 34696502, 2021). "At 2 days after infection, EBV markedly induced expression of MYC, CD21, CD23, HES1, and BATF (positive controls) 10- to 20-fold, possibly through EBNA2; in contrast, host housekeeping genes including β-2 microglobulin (B2M) and RNA polymerase II (POLR2A) were unaffected." (PMID 30487153, 2018).
neurodevelopmental disorder (4 papers, 2022 to 2023). A behavioral and cognitive disorder with onset during the developmental period that involves impaired or aberrant development of intellectual, motor, or social functions. "Our study and previously published cohorts of patients with POLR2A variants demonstrate the diagnostic utility of next-generation sequencing as it pertains to ASD and other neurodevelopmental disorders." (PMID 35328024, 2022).
POLR2A also shares sentences with these, for which no sentence is quoted: clear cell renal cell carcinoma (3 papers); osteosarcoma (3); triple-negative breast carcinoma (3); Intellectual disability (2); Psammomatous Meningioma (2); adrenal hyperplasia (1); Angiomatous Meningioma (1); behavioral disorders (1); Clear Cell Meningioma (1); co-infection (1); Cockayne syndrome (1); Cockayne Syndrome A (1); colon adenocarcinoma (1); cutaneous melanoma (1); diabetic kidney disease (1); Down syndrome (1); embryonal carcinoma (1); epidermoid carcinoma (1); familial meningioma (1); fibrosis (1); Gait ataxia (1); head and neck squamous cell carcinoma (1); hematological tumors (1); Huntington disease (1); Hydrocephalus (1); immune dysfunction (1); infarction (1); invasive carcinoma (1); ischemic disease (1); leukemia (1).
A further 19 diseases each share a sentence with POLR2A in 1 paper.